CHN1 (chimerin 1)
Description:
GTPase-activating protein for p21-rac and a phorbol ester receptor. Involved in the assembly of neuronal locomotor circuits as a direct effector of EPHA4 in axon guidance.
Synonyms: NC; ARHGAP2; CHN; RhoGAP2; n-chimerin; DURS2
Tractability: PROTAC: ubiquitination databases record sites on it; its protein half-life has been measured.
Gene: Protein-coding gene on chromosome 2 (174,798,809 to 175,005,381, reverse strand). Ensembl gene ENSG00000128656.
Subcellular location (Human Protein Atlas): Cytosol
Pathways (Reactome):
Signal Transduction: CDC42 GTPase cycle; RAC1 GTPase cycle
Gene Ontology:
Molecular function: protein binding; ephrin receptor binding; GTPase activator activity
Biological process: ephrin receptor signaling pathway; motor neuron axon guidance; regulation of axonogenesis; regulation of small GTPase mediated signal transduction; signal transduction
Cellular component: cytosol
Genetic constraint (gnomAD): Loss-of-function variants: 16 observed, 30.75 expected, observed/expected ratio (o/e) 0.52, 90% interval 0.35 to 0.79. The upper end of that interval is the gene's LOEUF score, 0.79, which puts it in group 3 of 6, group 1 being the genes least tolerant of losing a copy. Missense variants: 364 observed, 452.37 expected, observed/expected ratio (o/e) 0.8, 90% interval 0.74 to 0.88. Synonymous variants: 166 observed, 164 expected, observed/expected ratio (o/e) 1.01, 90% interval 0.89 to 1.15.
Gene-disease validity (ClinGen):
ClinGen rates the evidence that CHN1 causes each of these diseases.
Duane retraction syndrome 2 (autosomal dominant): Moderate.
Homologues: Orthologues: chimpanzee CHN1 (100% identical), macaque CHN1 (99% identical), pig CHN1 (99% identical), rabbit CHN1 (98% identical), mouse Chn1 (96% identical), rat Chn1 (96% identical), zebrafish chn1 (87% identical), rat AABR07032856.1 (58% identical), Caenorhabditis elegans chin-1 (37% identical), Drosophila melanogaster RhoGAP5A (19% identical). Paralogues in human: CHN2 (73% identical), SYDE2 (24% identical), ARHGAP35 (22% identical), SYDE1 (21% identical).
Diseases named in the same sentence as CHN1 in open-access papers:
CHN1 is named in the same sentence as 45 diseases in open-access papers, as found by Europe PMC text mining. Sharing a sentence is not in itself a finding about the gene and the disease. The quoted sentences say what the papers report.
Duane retraction syndrome (8 papers, 2011 to 2024). Duane retraction syndrome (DRS) is a congenital form of strabismus characterized by horizontal eye movement limitation, globe retraction and palpebral fissure narrowing in attempted adduction. "Although most cases do not have an identifiable genetic cause, autosomal dominant variants in CHN1 or MAFB can cause isolated Duane syndrome, and variants in SALL4 cause Duane-radial ray syndrome (Duane syndrome plus abnormalities of forearm development)." (PMID 38500555, 2023). "One form of familial Duane syndrome can be caused by a heterozygous mutation in chimerin 1 (CHN1)." (PMID 21850174, 2011). "CHN1 is well investigated in Duane retraction syndrome (DRS), in which CHN1 mutations have been identified in patients, and it is believed to have a crucial developmental function in this disorder." (PMID 34238315, 2021). "For example, the responsible gene in Duane Retraction Syndrome (CHN1) is involved in ocular motor axon path finding of the sixth nerve." (PMID 23419067, 2013). "Regarding Duane retraction syndrome, which can be considered a congenital cranial dysinnervation disorder, a dominant familial form (DURS2) was linked in a large pedigree to 2q31 and is now known to be caused by heterozygous mutation in chimerin 1 (CHN1)." (PMID 21541264, 2011). "However, heterozgyous CHN1 mutation is a rare cause of Duane syndrome and is not relevant for most of Duane syndrome patients encountered in pediatric ophthalmology clinical practice." (PMID 21541264, 2011). "However, most patients with Duane retraction syndrome do not have mutation in CHN1." (PMID 21850174, 2011).
cervical carcinoma (6 papers, 2020 to 2025). A carcinoma arising from either the exocervical squamous epithelium or the endocervical glandular epithelium. "For example, overexpression of CHN1 gene in cervical cancer was associated with accelerated cancer cell invasion, migration and tumor progression." (PMID 40382536, 2025). "We found that the intensity of CHN1 expression was significantly associated with lymph node metastasis of cervical cancer (P = 0.008)." (PMID 33109127, 2020). "Thus, overall, these results demonstrated that high miR-205 expression was associated with high CHN1 expression, and vice versa, in the cervical cancer cell lines." (PMID 33109127, 2020). "Downregulation of miR-205 directly targets and upregulates CHN1 expression, consequently suppressing apoptotic processes in cervical cancer cells." (PMID 41001034, 2025). "To date, there have been few reports on CHN1 in tumors, but CHN1 has been found to play an oncogenic role in cervical cancer." (PMID 34152250, 2021). "Since pelvic lymph node metastasis is one of the common types of cervical cancer progression, we then detected the correlation between the metastasis of lymph nodes and CHN1 expression by IHC." (PMID 34238315, 2021). "In this study, the carcinogenesis of CHN1 was investigated to determine its role in the occurrence and development of cervical carcinomas." (PMID 34238315, 2021). "In the present study, we demonstrated that CHN1 is highly expressed in cervical carcinoma and is correlated with long-term prognosis." (PMID 34238315, 2021). "In contrast, an inhibitory effect was observed when CHN1 expression was interrupted, consistent with Liu’s previous finding that knockdown of CHN1 reduced aggressive cervical cancer cell behaviors." (PMID 34238315, 2021). "The aim of this study was to further investigate the role of CHN1 in the progression and metastasis of cervical carcinoma, and to reveal the potential mechanism by which CHN1 exerts its function." (PMID 34238315, 2021). "The high expression of CHN1 was observed in the metastatic lymph nodes of cervical carcinoma tissue." (PMID 34238315, 2021). "As CHN1 was highly expressed in cervical carcinoma tissues, the influence of its upregulation on cell proliferation was then tested by establishing a CHN1-high expression model in the SiHa and HeLa cell lines." (PMID 34238315, 2021). "As this is the first study to demonstrate the role of CHN1 in cervical cancer, further studies are required to validate these results." (PMID 33109127, 2020). "In summary, miR-205 was specifically upregulated in cervical cancer, and positively regulated CHN1 to control cancer cell proliferation, invasion, and migration." (PMID 33109127, 2020). "Our findings showed that miR-205 positively regulated CHN1 to mediate cell growth, apoptosis, migration, and invasion during cervical cancer development, particularly for high-risk HPV-type cervical cancer." (PMID 33109127, 2020). "CHN1 mRNA expression was elevated in the cervical cancer tissues than in the adjacent tissues of cancer." (PMID 33109127, 2020). "In this study, for the first time, we demonstrated that miR-205 positively regulated the expression of CHN1 in cervical cancer and that miR-205-dependent upregulation of CHN1 promoted the proliferation, migration, and invasion of cervical cancer." (PMID 33109127, 2020). "Knockdown of CHN1 obviously reduced the aggressive cellular behaviours induced by upregulation of miR-205, suggesting that miR-205 positively regulated CHN1 to mediate these cell behaviours during the development of cervical cancer." (PMID 33109127, 2020). "To this end, we analysed the relationships between miR-205 and CHN1 expression and function in human cervical cancer tissues and cell lines." (PMID 33109127, 2020). "The expression levels and functions of miR-205/CHN1 varied in cervical cancer cell lines exhibiting different HPV types which are vital to cancer development." (PMID 33109127, 2020).
cervical carcinoma (continued). "We found that miR-205 and CHN1 were highly expressed in human cervical cancer tissue compared with paired normal cervical tissues." (PMID 33109127, 2020). "In this study, we aimed to elucidate the roles of microRNAs and a1-chimaerin (CHN1) protein in cervical cancer progression." (PMID 33109127, 2020). "The functions of miR-205-dependent CHN1 expression in the pathological processes of cervical cancer cells were examined." (PMID 33109127, 2020). "For example, in breast cancer, miR-205 inhibits EMT by specifically targeting ZEB1 and ZEB2, thereby exerting tumor suppressor effects; Whereas, in cervical cancer cells, up-regulation of miR-205 can significantly target and inhibit CHN1 expression levels, thereby promoting tumor cell proliferation." (PMID 41001034, 2025). "CHN1 was found to be highly expressed in the metastatic lymph nodes of cervical cancer tissues, which indicated that CHN1 might be related to cervical cancer metastasis." (PMID 34238315, 2021). "Thus, CHN1 can be considered as a novel marker of cervical carcinoma for the clinical diagnosis of metastasis and poor prognosis in CC patients." (PMID 34238315, 2021). "It showed that, both were stained in brown with similar localizations in tumor samples, which implied that the level of Snail might related to the expression of CHN1 during cervical cancer development." (PMID 34238315, 2021). "Our results have demonstrated that CHN1 and miR-205 might be used as biomarkers of human cervical cancer metastasis and potential therapeutic targets, and miR-205 positively regulated the expression of CHN1 in human cervical cancer." (PMID 33109127, 2020). "Our data supported that CHN1 and miR-205 might be biomarkers of human cervical cancer metastasis and potential therapeutic targets in human cervical cancer." (PMID 33109127, 2020). "Additionally, our studies showed that knockdown of CHN1 in SiHa cells blocked cancer-associated biological processes, further highlighting the importance of miR-205 and miR-205-dependent expression of CHN1 in cervical cancer development." (PMID 33109127, 2020). "In this study, we found that both CHN1 and miR-205 functioned as oncogenes in cervical cancer." (PMID 33109127, 2020). "The immunohistochemical analysis of CHN1 of 46 human cervical cancer samples were performed, to investigate the relationship between CHN1 overexpression and the clinical characteristics of human cervical cancer." (PMID 33109127, 2020). "Therefore, further studies are required to determine how different HPV types affect the expression and function of miR-205/CHN1 in cervical cancer." (PMID 33109127, 2020). "Therefore, we hypothesised that CHN1 might be regulated by miR-205 and involved in the development and metastasis of human cervical cancer." (PMID 33109127, 2020). "Therefore, regarding our current results, miR-205 may directly regulate CHN1 to affect F-actin expression, indirectly supporting the positive regulation of CHN1 by miR-205 in cervical cancer." (PMID 33109127, 2020). "To further analyse the differences between CHN1 expression and metastasis of cervical tumours, we investigated the expression of CHN1 in a microarray of cervical cancer tissues with or without lymph node metastasis." (PMID 33109127, 2020). "CHN1 is related to lymphoma and cervical carcinoma, though not previously studied in lung cancer." (PMID 40837413, 2025). "CHN1 can accelerate the occurrence of tumor biological behaviors and may stimulate the activation of EMT through the Akt/GSK-3β/Snail pathway to promote the metastasis of cervical carcinoma." (PMID 34238315, 2021). "Interestingly, transfection with miR-205 mimic upregulated CHN1 mRNA and protein, while miR-205 inhibitor downregulated CHN1 in high-risk and human papilloma virus (HPV)-negative human cervical cancer cells in vitro." (PMID 33109127, 2020).
Alzheimer disease (3 papers, 2020 to 2025). A progressive, neurodegenerative disease characterized by loss of function and death of nerve cells in several areas of the brain leading to loss of cognitive function such as memory and language. "Moreover, top hub genes in this module were associated with the development of Alzheimer’s disease, including VSNL1, INA, CHN1, NMNAT2, and MAP7D2." (PMID 37284017, 2023). "CHN1 was never reported as a linked gene to AD, but previous research studies found that disturbances in signal transduction mechanisms are associated with Alzheimer’s disease." (PMID 33282526, 2020).
Fabry disease (2 papers, 2025). Fabry disease (FD) is a progressive, inherited, multisystemic lysosomal storage disease characterized by specific neurological, cutaneous, renal, cardiovascular, cochleo-vestibular and cerebrovascular manifestations. "Promoter-level transcriptome analysis alongside artificial intelligence (AI) algorithms was employed to identify the chimerin 1 (CHN1) gene as a potential biomarker for cardiac issues in 15 male individuals with Fabry disease." (PMID 41150803, 2025).
lymph node metastasis (2 papers, 2020 to 2021). "CHN1 was overexpressed in CC tissues and was associated with lymph node metastasis and low survival in CC patients." (PMID 34238315, 2021). "Furthermore, CHN1 was correlated with lymph node metastasis in clinical specimens." (PMID 33109127, 2020). "CHN1 level was related to lymph node metastasis (p = 0.003), but not with the age, clinical stage, or histological differentiation of patients." (PMID 34238315, 2021).
psoriasis (2 papers, 2022 to 2025). An autoimmune condition characterized by red, well-delineated plaques with silvery scales that are usually on the extensor surfaces and scalp. "Within the set of psoriasis-specific skin-resident DEGs that are overexpressed relative to analogous T cells in atopic dermatitis, examples of such lower variance Th17 biomarkers include the GTPase-activator CHN1 (0.069) and PTMS (0.077)." (PMID 35958578, 2022).
allergic disease (1 paper, 2024). An immune response that occurs following re-exposure to an innocuous antigen, and that requires the presence of existing antibodies against that antigen. "Next, we investigated whether C. albicans was inducing a type 2 immune response in the glandular stomach, since we had previously shown that gastrointestinal colonization with C. albicans CHN1 can promote the development of allergic diseases in the airways." (PMID 39347572, 2024).
Congenital fibrosis of the extraocular muscles type 1 (1 paper, 2017). "Congenital fibrosis of the extraocular muscles type 1 (CFEOM1) is known to be caused by mutations in KIF21A or TUBB3 or other known genes (SALL4, CHN1, HOXA1)." (PMID 29110737, 2017).
depression (1 paper, 2025). "By employing bioinformatics and machine learning techniques, we identified CHN1 as a promising biomarker associated with depression in AD patients." (PMID 41333466, 2025). "Together, these findings reveal previously unrecognized immunoinflammatory axis underlying AD-associated depression, and shed light on CHN1 as a potential molecular bridge connecting peripheral inflammation and neuropsychiatric manifestations." (PMID 41333466, 2025). "We further pinpointed CHN1 as a potential biomarker closely linked to both the inflammatory response and depression severity." (PMID 41333466, 2025). "We further identified CHN1 as a key gene significantly upregulated in PBMCs of AD patients with depression." (PMID 41333466, 2025). "TheX3se findings suggested CHN1 as a potential biomarker of both lesion severity and psychological burden in AD patients with comorbid depression." (PMID 41333466, 2025). "The expression level of CHN1 demonstrated positive correlation with Th2 and Th17 cytokine signatures, as well as with the Hospital Anxiety and Depression Scale-Depression (HADS-D) score, and the Eczema Area and Severity Index (EASI)." (PMID 41333466, 2025). "In our validation cohort, qPCR and IHC confirm CHN1 upregulation in both peripheral blood and skin lesions of AD patients with depression." (PMID 41333466, 2025). "ROC analysis illustrated revealed that CHN1 and HEXD-IT1 exhibited high AUC values (> 0.8), indicating a strong association of these two genes with AD-related depression." (PMID 41333466, 2025). "Moreover, increased expression of CHN1 in skin lesions of AD patients with depression underscored CHN1’s potential as a biomarker or therapeutic target." (PMID 41333466, 2025). "Similarly, qPCR analysis demonstrated significantly higher levels of CHN1 expression in PBMCs of AD patients with depression." (PMID 41333466, 2025). "The limitation may restrict the generalizability of our findings and the robustness of validating CHN1 as a stable biomarker, particularly given the heterogeneity of immune pathway dysregulation among different subgroups of patients with AD and depression comorbidity." (PMID 41333466, 2025). "Furthermore, machine learning models of least absolute shrinkage and selection operator (LASSO) and support vector machine-recursive feature elimination (SVM-RFE) consistently identified CHN1 as a potential pivotal gene upregulated in AD patients with depression." (PMID 41333466, 2025). "From the pool of identified genes, CHN1 and HEXD-IT1 emerged as upregulated in AD patients with comorbid depression, whereas CXCR6 was pinpointed as a downregulated gene." (PMID 41333466, 2025). "IHC staining of the skin lesions revealed markedly stronger CHN1 expression in the lesion tissues of AD patients with depression compared to those without." (PMID 41333466, 2025).
food allergy (1 paper, 2024). Gastrointestinal disturbances, skin eruptions, or shock due to allergic reactions to allergens in food. "We used the same protocol described earlier for gastrointestinal colonization by C. albicans CHN1, followed by the induction of experimental food allergy (34, –, 37)." (PMID 39347572, 2024).
gastric cancer (1 paper, 2021). A primary or metastatic malignant neoplasm involving the stomach. "Our results showed that high CHN1 expression may regulate GC progression of gastric cancer through via multiple pathways and that CHN1 levels may influence the effectiveness of immunotherapy in GC." (PMID 34152250, 2021).
gastritis (1 paper, 2024). Inflammation of the stomach. "Collectively, these findings demonstrate that C. albicans CHN1 successfully colonizes the murine stomach and induces gastritis, but the inflammatory response is minimal in the glandular stomach mucosa." (PMID 39347572, 2024). "In this and previous work, we have demonstrated that C. albicans CHN1 colonization of the murine stomach results in highly regionalized gastritis of the limiting ridge." (PMID 39347572, 2024).
metastatic cancer (1 paper, 2025). A carcinoma which has spread from the original site of growth to another anatomic site. "The results showed that the expression levels of CLOCK, along with CBX5, CHN1, CNN3, FNDC1, PALLD, and SULF1, were significantly elevated in metastatic cancer tissues compared to primary cancer tissues." (PMID 41350567, 2025).
neuroblastoma (1 paper, 2020). Neuroblastoma (NB) is the most common solid, extracranial childhood tumor. "Interestingly, microinjected CHN1 colocalised in situ with F-actin in Swiss3T3 and neuroblastoma cells." (PMID 33109127, 2020).
oral candidiasis (1 paper, 2021). Infection of the mucosal lining of the mouth with the fungus Candida albicans. "We note that 529L was obtained from a patient with oral candidiasis while CHN1 was isolated from the human lung, indicating that these strains were not isolated from the intestinal tracts of their respective hosts." (PMID 34724818, 2021).
viral disease (1 paper, 2021). "YLD is a very common viral disease, and at least six SCYLV genotypes (BRA, CHN1, CHN2, CHN3, CUB, and PER or HAW) occurr in China28,30,31,35." (PMID 33785787, 2021).